PAX6 (paired box 6)
Description:
Transcription factor with important functions in the development of the eye, nose, central nervous system and pancreas. Required for the differentiation of pancreatic islet alpha cells (By similarity). Competes with PAX4 in binding to a common element in the glucagon, insulin and somatostatin promoters. Regulates specification of the ventral neuron subtypes by establishing the correct progenitor domains (By similarity). Acts as a transcriptional repressor of NFATC1-mediated gene expression (By similarity).
Synonyms: AN2; D11S812E; AN; WAGR; AN1; ASGD5; FVH1; MGDA
Tractability: PROTAC: UniProt records ubiquitination sites on it; ubiquitination databases record sites on it; its protein half-life has been measured.
Gene: Protein-coding gene on chromosome 11 (31,784,779 to 31,817,961, reverse strand). Ensembl gene ENSG00000007372.
Subcellular location: Nucleus; Nucleus (Isoform 1); Nucleus (Isoform 5a)
Subcellular location (Human Protein Atlas): Nucleoplasm
Pathways (Reactome):
Developmental Biology: Activation of anterior HOX genes in hindbrain development during early embryogenesis; Formation of the anterior neural plate; Regulation of gene expression in beta cells
Metabolism of proteins: Synthesis, secretion, and inactivation of Glucagon-like Peptide-1 (GLP-1); Synthesis, secretion, and inactivation of Glucose-dependent Insulinotropic Polypeptide (GIP)
Gene Ontology:
Molecular function: DNA-binding transcription activator activity, RNA polymerase II-specific; DNA-binding transcription factor activity, RNA polymerase II-specific; protein binding; R-SMAD binding; RNA polymerase II cis-regulatory region sequence-specific DNA binding; sequence-specific double-stranded DNA binding; DNA binding; DNA-binding transcription factor activity; histone acetyltransferase binding; protein kinase binding; transcription cis-regulatory region binding; transcription coregulator binding; chromatin binding; chromatin DNA binding; co-SMAD binding; DNA-binding transcription repressor activity, RNA polymerase II-specific; HMG box domain binding; RNA binding; RNA polymerase II core promoter sequence-specific DNA binding; sequence-specific DNA binding; ubiquitin protein ligase binding
Biological process: blood vessel development; cornea development in camera-type eye; glucose homeostasis; iris morphogenesis; nervous system development; pancreatic A cell development; positive regulation of DNA-templated transcription; positive regulation of gene expression; positive regulation of miRNA transcription; positive regulation of transcription by RNA polymerase II; response to wounding; animal organ morphogenesis; brain development; central nervous system development; eye development; forebrain development; negative regulation of neurogenesis; negative regulation of transcription by RNA polymerase II; neuron fate commitment; regulation of transcription by RNA polymerase II; retina development in camera-type eye; sensory organ development; type B pancreatic cell differentiation; ventral spinal cord development; visual perception; and 7 more
Cellular component: chromatin; cytoplasm; nucleoplasm; nucleus
Genetic constraint (gnomAD): Loss-of-function variants: 7 observed, 58.18 expected, observed/expected ratio (o/e) 0.12, 90% interval 0.067 to 0.23. The upper end of that interval is the gene's LOEUF score, 0.23, which puts it in group 1 of 6, group 1 being the genes least tolerant of losing a copy. Missense variants: 343 observed, 553.18 expected, observed/expected ratio (o/e) 0.62, 90% interval 0.57 to 0.68. Synonymous variants: 199 observed, 203.06 expected, observed/expected ratio (o/e) 0.98, 90% interval 0.87 to 1.1.
Gene-disease validity (ClinGen):
ClinGen rates the evidence that PAX6 causes each of these diseases.
PAX6-related ocular dysgenesis (autosomal dominant): Definitive. Any eye disorder in which the cause of the disease is a mutation in the PAX6 gene.
Homologues: Orthologues: chimpanzee PAX6 (100% identical), guinea pig PAX6 (99% identical), rabbit PAX6 (99% identical), tropical clawed frog pax6 (98% identical), mouse Pax6 (97% identical), rat Pax6 (96% identical), pig PAX6 (96% identical), zebrafish pax6a (95% identical), zebrafish pax6b (93% identical), macaque PAX6 (89% identical), dog PAX6 (83% identical). Paralogues in human: PAX7 (23% identical), NOBOX (22% identical), PAX3 (21% identical), ARX (19% identical), RAX (17% identical), PAX4 (17% identical), OTP (17% identical), UNCX (16% identical), PAX2 (16% identical), ALX3 (16% identical), ALX4 (16% identical), PAX5 (16% identical), and 38 more.
Diseases named in the same sentence as PAX6 in open-access papers:
PAX6 is named in the same sentence as 282 diseases in open-access papers, as found by Europe PMC text mining. Sharing a sentence is not in itself a finding about the gene and the disease. The quoted sentences say what the papers report.
aniridia (253 papers, 2005 to 2026). Aniridia is a congenital ocular malformation characterized by the complete or partial absence of the iris. "Congenital aniridia, a rare disorder caused by PAX6 haploinsufficiency, is characterized by progressive, vision-threatening aniridia-associated keratopathy (AAK) with limbal epithelial dysfunction and chronic inflammation." (PMID 42048350, 2026). "PAX6 haploinsufficiency-related congenital aniridia is frequently associated with ocular surface disease, including meibomian gland dysfunction (MGD), dry eye, limbal stem cell deficiency (LSCD), aniridia-associated keratopathy (AAK), and inflammation." (PMID 41752876, 2026). "For example, the mutation p.Ile87Arg in PAX6 leads to loss of DNA binding, causing an aniridia phenotype through haploinsufficiency." (PMID 40998763, 2025). "Mutations in Pax6 lead to ocular malformations in both vertebrates and invertebrates, with PAX6 mutations in humans causing aniridia." (PMID 41210874, 2025). "Haploinsufficiency of the PAX6 gene is the primary pathogenic mechanism underlying classical congenital aniridia." (PMID 40828815, 2025). "Haploinsufficiency of PAX6 proteins leads to aniridia and limbal stem cell deficiency and eventually visual impairment." (PMID 40216818, 2025). "Congenital aniridia is a complex hereditary ocular developmental disorder, primarily caused by mutations in the PAX6 gene, resulting in reduced PAX6 gene and protein expression." (PMID 40828815, 2025). "Haploinsufficiency of the PAX6 gene causes aniridia, a congenital eye disorder characterised by the absence or malformation of the iris and foveal hypoplasia." (PMID 40133207, 2025). "Heterozygosity for mutations in the human PAX6 locus causes aniridia, a condition characterized by the complete or partial loss of the iris, resulting in severe visual impairment." (PMID 39902612, 2025). "Recent advancements in next‐generation sequencing (NGS) have significantly enhanced the identification of variants in the PAX6 gene, which is associated with aniridia and other ocular disorders." (PMID 40133207, 2025). "Mutation in the PAX6 gene is the most common cause of congenital aniridia, but other causative mutations exist." (PMID 40892309, 2025). "For disease modeling, CRISPR/Cas9 and TALEN approaches have successfully recapitulated human ocular pathologies including aniridia (Pax6 mutations), retinitis pigmentosa (RHO variants), and congenital cataracts (GJA8 defects)." (PMID 41210874, 2025). "Since aniridia is primarily associated with PAX6 haploinsufficiency, therefore, siRNA PAX6 knockdown can mimic aniridia PAX6 deficiency in pLECs." (PMID 40493651, 2025). "As most cases of congenital aniridia result from heterozygote mutation in PAX6 gene, this can explain the diverse manifestations of the condition." (PMID 41343530, 2025). "Heterozygous loss-of-function variants in PAX6 can cause a range of ophthalmic disorders including aniridia." (PMID 38849599, 2024). "Nonsense and missense mutations in the transcription factor PAX6 cause a wide range of eye development defects, including aniridia, microphthalmia and coloboma." (PMID 38849565, 2024). "Mice are an excellent model for congenital aniridia as the human PAX6 and mouse Pax6 genes are identical and encode the same amino acid sequence." (PMID 39625791, 2024). "Heterozygous mutations or deletions within PAX6 or adjacent regions are the major causes of aniridia, which can disrupt normal development of the eye." (PMID 39449022, 2024). "Among the 60 patients, 23 (23/60, 38.3%) were diagnosed with glaucoma at the first visit, similar to the reported 30–67% prevalence of glaucoma in PAX6-associated congenital aniridia." (PMID 39449022, 2024). "Congenital aniridia is a disorder of disrupted normal eye development owing to haploinsufficiency of the PAX6 protein caused by heterozygous mutations of the PAX6 gene." (PMID 39625791, 2024).
aniridia (continued). "Aniridia is a rare congenital ocular disorder, primarily resulting from PAX6 gene mutations, that significantly impacts visual function." (PMID 39518758, 2024). "The underlying cause of aniridia is a mutation in the PAX6 gene, a deletion that leads to a premature stop codon." (PMID 38673496, 2024). "Consistent with our findings upon Prdm15 KD, PAX6 gene mutations in humans are associated with eye defects such as aniridia and corneal opacification or cataract." (PMID 38444828, 2024). "In summary, the present mouse model provides the potential to elucidate diverse pathophysiologic mechanisms in the most prevalent PAX6 mutation type observed in congenital human aniridia." (PMID 39625791, 2024). "The genetic basis of aniridia has been the subject of numerous studies, leading to the development of innovative therapeutic options based on PAX6 nonsense mutations." (PMID 39449022, 2024). "The third, and possibly most exciting, advantage of WGS in the diagnostic investigation of classic aniridia is the ability to identify causative cis-regulatory variants affecting the developmental expression of PAX6." (PMID 38050128, 2024). "Pathogenic variants of PAX6 impair ocular development, resulting in phenotypes that are mainly characterized by aniridia, foveal hypoplasia, kerathopathy, cataracts, and glaucoma." (PMID 39766826, 2024). "The PAX6 gene is located on chromosome 11p13, and its loss of function mutation (haploinsufficiency) is responsible for about 90% of aniridia cases." (PMID 38594720, 2024). ">90% of cases of classic aniridia are caused by heterozygous, loss-of-function variants affecting the PAX6 locus." (PMID 38050128, 2024). "Pax6, the major gene controlling ophthalmology development, was found to be responsible for limbal cell deficiency in congenital aniridia eyes." (PMID 38263030, 2024). "Aniridia is a rare congenital condition of abnormal eye development arising principally from heterozygous mutation of the PAX6 gene." (PMID 39625791, 2024). "As about 70% of all human cases of aniridia result from premature termination codon (PTC) mutations leading to nonsense-mediated PAX6 protein decay, this mutation type is the most useful for investigating disease mechanisms." (PMID 39625791, 2024). "While heterozygous nonsense mutations in PAX6 typically lead to aniridia, missense mutations cause diverse phenotypes that include microphthalmia, anophthalmia, and coloboma (MAC), isolated foveal hypoplasia, and congenital nystagmus." (PMID 38849565, 2024). "Congenital aniridia is a rare eye disease characterized by loss of PAX6 protein leading to aniridia-associated keratopathy that significantly reduces vision." (PMID 39488562, 2024). "In one case, a patient with biallelic PAX6 mutations from two parents with aniridia was born with microphthalmia, an abnormally small size of one or both eyes." (PMID 38473380, 2024). "A majority of aniridia cases are connected to a PAX6 mutation; a 2008 study found that of 125 patients with aniridia, 94% had a detectable mutation at the PAX6 genomic locus." (PMID 38473380, 2024). "Isolated aniridia can be caused by point mutations in the PAX6 gene (aniridia type 1), ELP4 gene (chromosome 11p13) (aniridia type 2), and TRIM44 gene (chromosome 11p13) (aniridia type 3)." (PMID 39600756, 2024). "Another cause of developmental glaucoma is aniridia, a rare eye disease characterized by an iris development anomaly and sporadic or dominant inheritance: the disease is caused by PAX6 mutations." (PMID 39766826, 2024). "The aniridia is due to PAX6 gene deletion, whereas Wilms tumor predisposition is due to WT1 gene deletion." (PMID 39600756, 2024). "In conclusion, our data certainly reiterate the notion that PAX6 alterations are primarily associated with the development of isolated aniridia." (PMID 38459225, 2024). "They consider mutation in the PAX6 gene to be the primary etiology concerned with both limbal stem cell deficiency and aniridia." (PMID 39149643, 2024).
aniridia (continued). "This study confirmed that variations in PAX6 and its adjacent regions were the predominant causes of congenital aniridia." (PMID 39449022, 2024). "This provides new evidence of the importance of positional effects of enhancers as pathogenic mechanisms leading to PAX6 deregulation underlying congenital aniridia." (PMID 37269011, 2023). "Aniridia is a rare congenital eye disorder, which is caused by autosomal dominant variants in the paired box 6 (PAX6) gene." (PMID 37072572, 2023). "Mutations in the PAX6 gene cause a series of ocular diseases, such as nystagmus, cataracts, and aniridia." (PMID 36983625, 2023). "In our study, approximately 64% (29/45) of the patients with the PAX6 variants showed typical clinical features of congenital aniridia, while other patients with PAX6 variants showed variable clinical features." (PMID 36816037, 2023). "Patients with typical aniridia, foveal hypoplasia, and nystagmus carry either an intragenic PAX6 variant that induces the NMD process or a large deletion involving PAX6." (PMID 37542296, 2023). "It expands the mutation spectrum of PAX6-related congenital aniridia, which is beneficial for prenatal diagnosis, genetic counseling, and gene therapy for familial cases in the near future." (PMID 36983625, 2023). "Both loss-of-function and missense mutations in PAX6 are known to cause aniridia, a severe eye abnormality, as well as a range of congenital eye defects." (PMID 36202929, 2023). "Although the co-occurrence of diabetes with aniridia was first reported in 2002, few studies have systematically looked at the prevalence of diabetes in individuals with pathogenic PAX6 mutations." (PMID 36202929, 2023). "Mutations in PAX6 are responsible for nearly 100% of the cases of congenital aniridia, a rare developmental disease characterized by abnormalities in the iris and fovea ⁠." (PMID 36881176, 2023). "In many of them, mutations in a single gene can explain most cases, e.g., PAX6 and aniridia ⁠, ABCA4 and Stargardt disease ⁠, or NF1 and Neurofibromatosis type 1 ⁠." (PMID 36881176, 2023). "Many studies have reported that mutations in the PAX6 gene and its regulatory regions are the leading cause of congenital aniridia." (PMID 37752489, 2023). "E1: the frequency at which we have found PAX6 mutations suggests that lesions in PAX6 will account for most cases of [aniridia]Disease." (PMID 37549065, 2023). "Taken together, this variant of PAX6 is a novel mutation which was most likely responsible for autosomal dominant congenital aniridia in this study." (PMID 36983625, 2023). "To test this, we examined the cell fate of LSCs from patients with aniridia, a disease mostly caused by PAX6 haploinsufficiency." (PMID 37856539, 2023). "Normal eye development depends on the presence of both copies of PAX6; therefore, loss of function in one of the two copies can lead to PAX6 haploinsufficiency, causing aniridia, which can be found in 80–90% of patients." (PMID 37542296, 2023). "Haploinsufficiency of the transcription factor PAX6 is the main cause of congenital aniridia, a genetic disorder characterized by iris and foveal hypoplasia." (PMID 37269011, 2023). "We identified a novel microdeletion, 517 kb in size located about 133 kb downstream of the PAX6 gene, responsible for congenital aniridia in this Chinese family, which expands the spectrum of aniridia-associated mutations in PAX6." (PMID 37752489, 2023). "Deficiency in PAX6 gene can result in a wide range of congenital eye anomalies, among which the most common are aniridia, nystagmus, and foveal hypoplasia, with cataracts being usually reported as an accompanied disorder." (PMID 36843716, 2023). "In recent years, many studies have focused on the varied clinical manifestation and allelic heterogeneity of PAX6-associated aniridia." (PMID 36983625, 2023). "We report our findings in 17 patients with PAX6 mutations associated with FVH1 or FH with aniridia and corneal opacities." (PMID 37510387, 2023).